INS (insulin)
Diseases named in the same sentence as INS in open-access papers (continued):
Sharing a sentence is not in itself a finding about the gene and the disease.
MODY (continued). "Rare variants in genes associated with MODY also demonstrated aggregate association with lower body-mass index (minimum P = 5.7 × 10−3) and lower fasting insulin (minimum P = 0.028), consistent with the known predominant variant risk mechanism of reduced insulin secretion in MODY23." (PMID 31118516, 2019). "Therefore, people with mutations in HNF1A or HNF4A causing MODY can be managed with low-dose sulphonylurea therapy, and those misdiagnosed may therefore potentially stop insulin injections or have tablet regimens rationalised." (PMID 30377832, 2018). "Studies have used iPSC-derived SC-islets to demonstrate how transcription factor dysfunction can perturb insulin secretion, beta cell maturation, and endocrine lineage specification in MODY subtypes." (PMID 42318217, 2026). "Here we share our own experience using GLP-1 RA and dual GIP/GLP-1 RA therapy in genetically confirmed MODY, with a focus on glycaemic control, weight, and the potential to reduce or stop sulfonylureas and insulin." (PMID 41262822, 2025). "Identifying GCK‐MODY in Family 202 prevents unnecessary administration of insulin or oral hypoglycemics, thus minimizing overtreatment." (PMID 41497485, 2025). "Mutations at the HNF4α binding site of MED25 are often associated with MODY, underscoring the role of MED25 in the HNF4α-mediated insulin secretion and associated diabetes." (PMID 40940746, 2025). "Maturity-onset diabetes of the young (MODY), particularly due to HNF1A variants, is usually treated with sulfonylureas or insulin." (PMID 41262822, 2025). "Following the diagnosis of HNF4A-MODY, the patient's treatment was switched from insulin to sulfonylureas, resulting in improved glycaemic control and time in range, along with an improved quality of life." (PMID 40486195, 2025). "Another variant at the same amino acid position (p.Pro33Thr) was shown to decrease binding to the INS promoter and reduce transcriptional activity in vitro, leading to a MODY phenotype." (PMID 41153735, 2025). "While INS variants are better known to cause permanent neonatal DM (PNDM), several pathogenic variants have been identified in patients with MODY." (PMID 39717432, 2025). "Previous studies have shown that it modulates the expression of several MODY genes, including insulin, GCK, ABCC8, PDX1, and PAX4." (PMID 40148250, 2025). "Establishing a genetic diagnosis will help physicians better characterize each type of MODY, guide therapeutic decisions, and avoid unnecessary insulin." (PMID 39717432, 2025). "As genetic testing becomes more available, early recognition of MODY is essential to guide targeted management, reduce unnecessary insulin use, and support screening of affected relatives." (PMID 41367451, 2025). "GLP-1 receptor agonists and dual GIP/GLP-1 receptor agonists improved glycaemic control, reduced body weight, and decreased insulin dependency in MODY patients." (PMID 41262822, 2025). "Most patients with INS-MODY reported in literature are insulin dependent, although with varying degree of insulin requirement." (PMID 39717432, 2025). "Another study in 2010 sequenced the INS gene in 116 MODY patients of European ancestry and similarly found a novel pathogenic variant (NC_000011.10(NM_000207.3) (INS):c.17G>A p.Arg6His)—in the same codon, within a Danish family." (PMID 39717432, 2025). "Treatment of MODY varies from lifestyle modification alone, to the use of oral hypoglycemic agents such as sulfonylureas, while some patients require lifelong insulin." (PMID 39717432, 2025). "In a patient suspected of MODY, a novel heterozygous variant (HG38, chr11:2160943A>T, c.29T>A, read depth: 143×) in the second exon of the INS gene was identified, resulting in the amino acid substitution p.(Leu10Gln)." (PMID 39859454, 2025). "Mutations in seven of these genes, including ABCC8, GCK, HNF1B, INS, KCNJ11, NEUROD1, and PDX1, are implicated in both NDM and MODY." (PMID 39859454, 2025).
MODY (continued). "While mutations of the insulin gene (INS) are known to cause permanent neonatal DM, rare disease-causing variants have also been found in MODY." (PMID 39717432, 2025). "The patient with BLK-MODY was treated with a combination of metformin and insulin to achieve glycemic control." (PMID 39504571, 2025). "Lifestyle modifications and sulfonylureas are the first‐line therapy for some MODY subtypes, while insulin therapy is needed in other forms." (PMID 40716044, 2025). "Early and accurate diagnosis of MODY can significantly affect management by reducing unnecessary insulin use, improving glycemic control with oral agents, and guiding family screening." (PMID 40777711, 2025). "In view of his young age at onset, absence of antibodies, preservation of C-peptide, and having weaned off insulin, he was recruited for genetic testing for MODY using massive parallel sequencing method described." (PMID 39717432, 2025). "Although DKA is relatively rare, there are relevant reports, observed in some types of MODY, such as INS-, PDX1-, NEUROD1-, HNF1A- and HNF1B-MODY." (PMID 40303944, 2025). "The early neonatal period, insulin independence, and autosomal dominant inheritance are traditional features of MODY." (PMID 39902162, 2024). "Long-term use of sulfonylurea compounds has been observed to induce an increase in glucose-induced insulin secretion for up to 33 years in some patients with MODY." (PMID 39902162, 2024). "Patients with MODY1 have characteristic changes in the insulin secretory response to glucose, i.e., these patients are characterized by beta cell dysfunction, which differs from the clinical picture of MODY patients with glucokinase gene damage (MODY2)." (PMID 39902162, 2024). "It is remarkable that patients with MODY received more oral antidiabetic treatment in addition to insulin (77% received sulfonylurea and/or 54% metformin, with 69% receiving insulin)." (PMID 38792571, 2024). "This leads to misdiagnosis and the use of inadequate treatments, such as oral antidiabetics in a patient with T1D or high doses of insulin instead of the administration of oral antidiabetics in some patients with T2D or MODY." (PMID 38792571, 2024). "Patients with HNF1B-MODY often respond poorly to oral hypoglycemic agents such as sulfonylureas, with early insulin therapy required in up to 80% of cases." (PMID 39337310, 2024). "For example, mainly insulin in patients properly diagnosed as having T1D, sulfonylureas in patients with MODY, or a multi-treatment approach in patients with T2D." (PMID 38792571, 2024). "Maturity-onset diabetes of the young (MODY) is a mild familial diabetes mellitus with dominant inheritance, characterized by pancreatic β-cell destruction and disrupted insulin secretion." (PMID 38513803, 2024). "HNF1B-MODY is another type that is most frequently managed with insulin therapy but lacks a defined precision treatment." (PMID 38524636, 2024). "The diagnosis of MODY led to insulin cessation with transition to oral antidiabetic treatment with sulphonylurea while maintaining optimal glucose control." (PMID 39420387, 2024). "In relation to the time until the initiation of insulin therapy, only 3.51% of the patients with MODY began using insulin immediately following diagnosis, with the majority (86.6%) not currently using insulin." (PMID 36747290, 2023). "Correctly diagnosing MODY is important, as individuals with this diagnosis can discontinue insulin injections; however, many people are misdiagnosed." (PMID 37798422, 2023). "Regarding treatment, the percentage of patients with HNF1B-MODY treated with insulin was significantly higher than that of patients with HNF4A-MODY when compared with patients with T1DM (median 65.7% versus 36.4%, P = 0.00001 each)." (PMID 37016461, 2023). "Personalized management of each type of MODY results in better patient care and the avoidance of invasive therapies such as insulin in favor of more effective and economical treatments." (PMID 35246208, 2022).
MODY (continued). "MODY develops slowly and impairs insulin secretion so that the body cannot adequately control blood glucose levels." (PMID 35468151, 2022). "Some variants with substantial expression effects are associated with MODY, such as promoter mutations in GCK, HNF1A or HNF4A or neonatal diabetes with SNPs in the CC element of the INS promoter." (PMID 35008927, 2022). "Pathway analysis of differentially expressed genes in scβ-like cells revealed genes involved in MODY, endocrine cell development, calcium signaling/sensing, insulin secretion and synaptic vesicle cycle." (PMID 35918471, 2022). "We further found that for MODY patients, early intensive insulin therapy is also effective in improving islet function." (PMID 36181023, 2022). "Our study found that insulin was completely withdrawn in all the subjects with MODY in Group 1, 81.4% with T2DM, and 100% with GDM." (PMID 36339424, 2022). "Further work is needed to refine prediction tools, especially for MODY diagnosis in newly diagnosed patients on insulin or patients with young type 2 patients, and also individuals from non‐White ethnic groups." (PMID 35445424, 2022). "Both data sets identified differences in genes of the pathways of MODY, peptide secretion/insulin metabolism, and ER stress." (PMID 35925682, 2022). "Variability in insulin doses within families with MODY been reported previously, particularly in MODY types associated with β cell ER stress." (PMID 34032641, 2021). "Most MODY-associated genes, except GCK, encode for transcription factors involved in different manners in insulin secretion." (PMID 34681954, 2021). "In prospective studies, 20-50% of GCK-MODY patients were treated with oral hypoglycemic agents or insulin before the diagnosis was made." (PMID 35069449, 2021). "Low carbohydrate diet or low-dose sulfonylureas are used to manage HNF4A-MODY initially but insulin therapy is usually required in advanced disease or during pregnancy." (PMID 33292863, 2020). "A study demonstrated that 80% of patients with HNF1A-MODY treated with sulfonylurea therapy remained insulin independent at 84 months of follow-up." (PMID 32528556, 2020). "The INS gene demonstrated the highest percentage of interconnectedness in the three gene networks for T1D (1.59%), T2D (1.60%), and MODY (2.61%)." (PMID 33113859, 2020). "Management of MODY is subtype-specific and established treatment options include diet, oral antidiabetic drugs, or insulin." (PMID 33292863, 2020). "Clinically, KLF11-MODY presents as early-onset diabetes mellitus and is managed with OADs or insulin." (PMID 33292863, 2020). "Established treatment options for MODY include various glucose-lowering medications such as sulfonylureas, meglitinides, and insulin." (PMID 33292863, 2020). "A total of 4.1% of individuals had likely pathogenic or pathogenic variants in the commonest MODY genes (HNF1A, HNF4A, HNF1B, GCK or INS)." (PMID 30377832, 2018). "Based on previous reports, MODY is included in a group of genetic defects in the pancreatic β-cells limiting the ability of pancreas to produce insulin required for glucose utilization." (PMID 29867778, 2018). "C-peptide levels, a marker of endogenous insulin production, have also been used to help segregate people with type 1 diabetes (where C-peptide is low or undetectable) from those with MODY." (PMID 30377832, 2018). "There are two main treatment options for HNF1A MODY in pregnancy: stop sulfonylureas pre‐pregnancy and transfer to insulin or treat with glibenclamide pre‐/early pregnancy and transfer to insulin in the second trimester." (PMID 28556992, 2017). "GCK-MODY patients present with good, sometimes even high, insulin production and function but have increased set point stimulated insulin secretion." (PMID 28663157, 2017). "In contrast, there is a lack of glycaemic response with oral hypoglycaemic agents or low-dose insulin in patients with GCK-MODY." (PMID 28314945, 2017).
MODY (continued). "The traditional criteria of MODY (diabetes diagnosis <25 years, non-insulin treated and an affected parent) identify only 48% of MODY cases and, hence, are not sufficiently sensitive to be used alone in clinical practice." (PMID 28314945, 2017). "Patients with HNF1B-MODY require insulin treatment as the response to sulfonylureas and other oral medication is limited." (PMID 28314945, 2017). "Consistent with this, several genes associated with MODY have well-characterized functions in glucose homeostasis, including the glycolytic enzyme Glucokinase (GCK/MODY2), and Insulin (INS/MODY10)." (PMID 27185732, 2016). "It is well established that patients with HNF1A MODY are very sensitive to sulphonylureas (SU) and can be taken off insulin treatment after the proper molecular diagnosis." (PMID 26942212, 2016). "Mutations in genes like pancreatic and duodenal homeobox 1 (PDX1, MODY4), hepatocyte nuclear factor 1 beta (HNF1B, MODY5) neurogenic differentiation 1 (NEUROD1, MODY6) and insulin (INS, MODY10) cause relatively rare forms of MODY." (PMID 26300908, 2015). "In this study, we investigated the biological and structural relationship of the naturally occurring insulin mutant [GlnB22]-insulin, which is responsible for development of MODY." (PMID 25423173, 2014). "As our patient has been diagnosed at a very early stage of MODY, it is possible that his insulin secretion as assessed by intravenous glucose tolerance test is still preserved." (PMID 24299156, 2014). "Here we report the identification of MED25 as one of the HNF4α binding partners in pancreatic ß-cells leading to insulin secretion which is impaired in MODY patients." (PMID 22952853, 2012). "Since sulfonylureas (SU), the oldest group of oral hypoglycemic agents, act on the beta cell and enhance insulin secretion, the notion that the latter group are the drugs of choice in MODY was very appealing." (PMID 22996131, 2012). "MODY patients fail to properly secrete insulin in response to glucose challenge and β-cell-specific knockout of HNF4α in mice results in reduced GSIS." (PMID 22359515, 2012). "According to this point and the laboratory results; fasting blood glucose, fasting serum insulin HbA1c, and being well controlled patients, sensitivity of oral hypoglycemic agents in our MODY patients is noticeable." (PMID 20003313, 2009). "HNF4α's role in MODY originates from its function as a β cell transcription factor that influences glucose induced insulin secretion." (PMID 20003313, 2009). "Both MODY and T2D patients, have reduced insulin sensitivity as a result of pancreatic β cell dysfunction." (PMID 20003313, 2009). "Pregnancy management in patients with RFX6-MODY is similar to type 2 DM, although higher insulin doses may be required." (PMID 41636221, 2026). "Four patients (Patients 13, 14, 16 and 17) with INS-MODY experienced an increase in insulin dosage with age, suggesting that the cumulative effect of ER stress was related to the degree of pathological changes due to variants causing further damage to pancreatic islet cells with age." (PMID 40303944, 2025). "The estimated probability of MODY was 12.6% (≥10% for insulin-treated patients)." (PMID 41020216, 2025). "Sulfonylureas, particularly in HNF1A-related MODY, are effective and may obviate the need for insulin." (PMID 40777711, 2025). "Both mouse and human islets expressing TALK-1 Leu114Pro exhibited significantly reduced glucose-stimulated insulin secretion compared to those expressing the wild-type, suggesting that KCNK16 May be a novel pathogenic gene for MODY." (PMID 40650956, 2025). "MODY results from defects in pancreatic islet cell development, which impair insulin secretion." (PMID 40149950, 2025). "Patients with MODY typically test negative for autoantibodies (such as islet cell antibody, insulin autoantibody, insulinoma-associated protein-2 autoantibody, zinc transporter autoantibody, and glutamic acid decarboxylase antibody)." (PMID 40149950, 2025).
MODY (continued). "For MODY, this could involve correcting the specific mutations in genes like HNF1A or GCK, restoring normal insulin production and function." (PMID 39310514, 2024). "Key steps of insulin biosynthesis and secretion are regulated by transcriptional network constituting of hierarchical, auto- and inter-regulatory complex of transcription factors (TFs), some of which involved in the pathogenesis of MODY." (PMID 37255971, 2023). "At the time of diagnosis, diet or OADs may be used as a treatment for patients with MODY, but they eventually become insulin dependent." (PMID 36361703, 2022). "For instance, we might accept a high cost per detected mutation when a positive result may lead to a more tailored treatment approach, such as HNF1A‐MODY, which can be efficiently managed with sulphonylureas instead of insulin." (PMID 35822264, 2022). "Along with MODY genes, KCNQ1 mutations could influence T2DM by decreasing pancreatic β-cell mass and insulin secretion as per the present study." (PMID 35956399, 2022). "On the whole, most MODY patients are submitted to sulfonylureas, metformin, or insulin treatment." (PMID 36361703, 2022). "ABCC8 mutations can cause MODY in patients whose clinical features are similar to those with HNF1A/4AMODY, and some patients with ABCC8 mutations were able to change from insulin to oral glibenclamide therapy, which means that patients with ABCC8presented with T2DM-like phenotypes." (PMID 35992135, 2022). "Is there a cut-off for insulin or C-peptide to exclude MODY?" (PMID 34951657, 2022). "This strict definition is now outdated, since MODY also occurs in middle age and/or overweight/obese patients and may need insulin as the most appropriate treatment." (PMID 35052457, 2022). "In a study of Italian children with GCK-MODY, individual differences in insulin sensitivity but not molecular severity of GCK mutations affected the 2-hour post-load blood glucose level during OGTT." (PMID 34630320, 2021). "Insulin sensitivity is usually considered to be unaffected in GCK-MODY patients." (PMID 35069449, 2021). "Management of MODY is subtype-specific and includes diet, oral antidiabetic drugs, or insulin." (PMID 33292863, 2020). "Maturity-onset diabetes of the young (MODY) is а group of non-autoimmune diabetes caused by a single gene mutation that leads to a defect in the glucose-stimulated insulin secretion from the pancreatic beta-cells." (PMID 31137773, 2019). "The onset of MODY is not dependent on insulin but is caused by mutations in several genes that result in defective beta cells." (PMID 29922517, 2018). "During this period, MODY was named as type 2 diabetes, which could be managed by diet, insulin, and oral drugs." (PMID 29867778, 2018). "Individuals with HNF1A- or HNF4A-MODY are optimally treated with low-dose sulfonylureas because of an increased pancreatic insulin secretory response to sulfonylureas and increased insulin sensitivity to the insulin secreted." (PMID 30229274, 2018). "To analyze the frequencies of the carriers of such mutations in our cohort, we analyzed genes (HNF1A, HNF4A, HNF1B, INS, ABCC8, and KCNJ11) in which a significant number of missense mutations have previously been reported in MODY, neonatal diabetes mellitus, or early onset diabetes." (PMID 29207974, 2017). "Thus, it is probable that the development of MODY in [GlnB22]-insulin-producing patients has two different, but related and overlapping, causes." (PMID 25423173, 2014). "We aimed to evaluate the prevalence and the disease-associated phenotype of INS mutations among diabetic patients diagnosed with MODY, anti-body negative T1D or GDM." (PMID 20226046, 2010). "In summary, our characterization of a mouse model with the human MODY-causing PDX1P33T mutation revealed a striking divergence from the human phenotype and highlighted the importance of PDX1’s disordered regions in mediating dynamic protein-protein interactions essential for insulin expression." (PMID 41199860, 2025).